PLA2G4B (phospholipase A2 group IVB)
Description:
Calcium-dependent phospholipase A1 and A2 and lysophospholipase that may play a role in membrane phospholipid remodeling. [Isoform 3]: Calcium-dependent phospholipase A2 and lysophospholipase. Cleaves the ester bond of the fatty acyl group attached to the sn-2 position of phosphatidylethanolamines, producing lysophospholipids that may be used in deacylation-reacylation cycles. Hydrolyzes lysophosphatidylcholines with low efficiency but is inefficient toward phosphatidylcholines. [Isoform 5]: Calcium-dependent phospholipase A1 and A2 and lysophospholipase. Cleaves the ester bond of the fatty acyl group attached to the sn-1 or sn-2 position of diacyl phospholipids (phospholipase A1 and A2 activity, respectively), producing lysophospholipids that may be used in deacylation-reacylation cycles. Can further hydrolyze lysophospholipids enabling complete deacylation. Has no activity toward alkylacyl phospholipids.
Synonyms: cPLA2-beta; HsT16992
Tractability: Small molecule: it belongs to a druggable protein family. Antibody: its Gene Ontology location is reachable by antibodies, with high confidence; UniProt places it where antibodies can reach, with medium confidence. PROTAC: a small molecule that binds it is known.
Target class: Enzyme; Hydrolase
Gene: Protein-coding gene on chromosome 15 (41,837,775 to 41,848,147, forward strand). Ensembl gene ENSG00000243708.
Subcellular location: Cytoplasm, cytosol (Isoform 3); Mitochondrion membrane; Early endosome membrane; Cytoplasm, cytosol (Isoform 5)
Pathways (Reactome):
Metabolism: Acyl chain remodelling of PC; Acyl chain remodelling of PE; Acyl chain remodelling of PG; Acyl chain remodelling of PS; Hydrolysis of LPC; Synthesis of PA
Cellular responses to stimuli: XBP1(S) activates chaperone genes
Gene Ontology:
Molecular function: phosphatidylcholine lysophospholipase activity; phospholipase A2 activity; calcium ion binding; calcium-dependent phospholipid binding; phospholipase A1 activity; phospholipase activity
Biological process: glycerophospholipid catabolic process; arachidonate metabolic process; calcium-mediated signaling; inflammatory response; parturition; phosphatidylglycerol acyl-chain remodeling; glycerophospholipid metabolic process; phospholipid catabolic process
Cellular component: cytosol; early endosome membrane; mitochondrial membrane; extracellular region; mitochondrial inner membrane
Genetic constraint (gnomAD): Loss-of-function variants: 123 observed, 97.15 expected, observed/expected ratio (o/e) 1.27, 90% interval 1.09 to 1.47. The synonymous counts are far from expectation, so gnomAD's model fits this gene poorly and the ratio says little. Missense variants: 1,155 observed, 1,012.6 expected, observed/expected ratio (o/e) 1.14, 90% interval 1.09 to 1.2. Synonymous variants: 518 observed, 433.35 expected, observed/expected ratio (o/e) 1.2, 90% interval 1.11 to 1.28.
Homologues: Orthologues: chimpanzee PLA2G4B (99% identical), macaque PLA2G4B (96% identical), dog PLA2G4B (85% identical), pig PLA2G4B (84% identical), rabbit PLA2G4B (84% identical), guinea pig PLA2G4B (83% identical), rat Pla2g4b (82% identical), mouse Pla2g4b (82% identical), tropical clawed frog pla2g4d (43% identical), zebrafish pla2g4f.2 (35% identical), zebrafish pla2g4f.1 (35% identical), tropical clawed frog jmjd7-pla2g4b (35% identical). Paralogues in human: PLA2G4D (50% identical), PLA2G4E (43% identical), PLA2G4F (41% identical), PLA2G4A (25% identical), PLA2G4C (17% identical).
Diseases named in the same sentence as PLA2G4B in open-access papers:
PLA2G4B is named in the same sentence as 17 diseases in open-access papers, as found by Europe PMC text mining. Sharing a sentence is not in itself a finding about the gene and the disease. The quoted sentences say what the papers report.
colon carcinoma (2 papers, 2022). "Notably, PLA2G4B was reported to be specifically upregulated in liver metastasis of colon carcinoma." (PMID 35795065, 2022).
schizophrenia (2 papers, 2016 to 2024). A major psychotic disorder characterized by abnormalities in the perception or expression of reality. "For instance, SNP rs1549637 in PLA2G4C, BanI SNP in the PLA2G4A locus, and SNP rs1648833 in PLA2G4B may contribute to the risk of schizophrenia." (PMID 27434078, 2016).
atopic dermatitis (1 paper, 2026). "Our findings establish a causal relationship between specific gut bacteria (Eubacterium eligens group) and atopic dermatitis risk while identifying seven key bridging genes (AKR1C2, GALE, GGH, NR4A1, PLA2G4B, TYMS) that connect gut microbial metabolites to skin pathology." (PMID 41556698, 2026).
histiocytic lymphoma (1 paper, 2017). "JMJD-PLA2G4B is a paralog gene of PLA2G4B and has been described previously in U937 cells, isolated from the histiocytic lymphoma, to encode a calcium-dependent phospholipase that hydrolyzes the phospholipids to lysophospholipids and fatty acids." (PMID 28030848, 2017).
lung adenocarcinoma (1 paper, 2022). A carcinoma that arises from the lung and is characterized by the presence of malignant glandular epithelial cells. "TRDMT1 and JMJD7.PLA2G4B genes were downregulated, while the other 10 genes were significantly overexpressed in lung adenocarcinomas compared with normal tissues." (PMID 35812404, 2022).
psoriasis (1 paper, 2022). An autoimmune condition characterized by red, well-delineated plaques with silvery scales that are usually on the extensor surfaces and scalp. "In addition, we further confirmed that PLA2 was commonly elevated in psoriasis, although the expression levels of PLA2G4B and PLA2G2F were incompatible with some previous studies, possibly due to sample size and individual variability." (PMID 36700214, 2022).
cancer (6 papers, 2017 to 2025). A tumor composed of atypical neoplastic, often pleomorphic cells that invade other tissues. "The JMJD7 gene, located on human chromosome 15, can form a naturally occurring read-through transcript with the neighbouring PLA2G4B gene to encode a JMJD7-PLA2G4B fusion protein overexpressed in cancers, including breast, prostate, and thyroid cancer." (PMID 35410347, 2022). "Mechanistically, FASN, which is upregulated in CRC tissues, drives cancer cell proliferation, metastasis, and PC metabolism through the SP1/PLA2G4B axis, subsequently suppressing the antitumor response of natural killer (NK) cells in a PC-dependent manner." (PMID 40148316, 2025). "Among the 850 hypoxia-related genes, 6 genes (LOC101928143, LOC102723407, MIR1281, PLA2G4B, SLC5A10, and G6PC1) were absent from the TCGA pan-cancer RNA-seq data; thus, 844 genes with RNA expression values were used in the analysis." (PMID 38248716, 2023).
tumor (3 papers, 2022 to 2025). "PLA2G4B expression was significantly correlated with tumor differentiation and survival." (PMID 40148316, 2025). "Curiously, a natural readthrough transcription between the JMJD7 locus and the downstream neighbor phospholipase A2, group IVB (PLA2G4B), occurs in tumor tissues, encoding the fusion protein JMJD7-PLA2G4B including a partial JmjC domain and the C2 and phospholipase A2 domains." (PMID 39000010, 2024).
infection (1 paper, 2022). The state of being infected such as from the introduction of a foreign agent such as serum, vaccine, antigenic substance or organism. "Several genes were significantly upregulated (Pla2g4a, Pla2g4c, Pla2g7, Ptgs1, Ptgs2, Pla1, Tbxas1) or downregulated (Alox5, Pla2g2d, Pla2g1b, Pla2g4b, Pla2g4f) during infection." (PMID 35812400, 2022).
mental illness (1 paper, 2022). "One previous study confirmed that another three family members, PLA2G4A, PLA2G4B, and PLA2G4C, are strongly associated with mental illness in the Chinese population." (PMID 36056316, 2022).
PLA2G4B also shares sentences with these, for which no sentence is quoted: head and neck squamous cell carcinoma (3 papers); alcoholic liver diseases (1); breast carcinoma (1); colorectal cancer (1); head and neck tumor (1); metabolic disorder (1); squamous cell carcinoma (1).